ATG4C (autophagy related 4C cysteine peptidase)
Description:
Cysteine protease that plays a key role in autophagy by mediating both proteolytic activation and delipidation of ATG8 family proteins. The protease activity is required for proteolytic activation of ATG8 family proteins: cleaves the C-terminal amino acid of ATG8 proteins MAP1LC3 and GABARAPL2, to reveal a C-terminal glycine. Exposure of the glycine at the C-terminus is essential for ATG8 proteins conjugation to phosphatidylethanolamine (PE) and insertion to membranes, which is necessary for autophagy (By similarity). In addition to the protease activity, also mediates delipidation of ATG8 family proteins. Catalyzes delipidation of PE-conjugated forms of ATG8 proteins during macroautophagy. Compared to ATG4B, the major protein for proteolytic activation of ATG8 proteins, shows weaker ability to cleave the C-terminal amino acid of ATG8 proteins, while it displays stronger delipidation activity. In contrast to other members of the family, weakly or not involved in phagophore growth during mitophagy.
Synonyms: HsAPG4C; APG4C; AUTL1; AUTL3; FLJ14867; APG4-C
Tractability: PROTAC: ubiquitination databases record sites on it; its protein half-life has been measured.
Gene: Protein-coding gene on chromosome 1 (62,783,821 to 62,865,999, forward strand). Ensembl gene ENSG00000125703.
Subcellular location: Cytoplasm
Subcellular location (Human Protein Atlas): Cytosol; Nucleoplasm
Pathways (Reactome):
Autophagy: Macroautophagy
Gene Ontology:
Molecular function: cysteine-type endopeptidase activity; cysteine-type peptidase activity; protein binding; protein-phosphatidylethanolamide deconjugating activity
Biological process: autophagosome assembly; autophagy; protein delipidation; proteolysis; aggrephagy; mitophagy; piecemeal microautophagy of the nucleus; protein processing
Cellular component: cytoplasm
Genetic constraint (gnomAD): Loss-of-function variants: 35 observed, 37.62 expected, observed/expected ratio (o/e) 0.93, 90% interval 0.71 to 1.23. The upper end of that interval is the gene's LOEUF score, 1.23, which puts it in group 5 of 6, group 1 being the genes least tolerant of losing a copy. Missense variants: 465 observed, 419.11 expected, observed/expected ratio (o/e) 1.11, 90% interval 1.03 to 1.2. Synonymous variants: 126 observed, 139.97 expected, observed/expected ratio (o/e) 0.9, 90% interval 0.78 to 1.04.
Homologues: Orthologues: chimpanzee ATG4C (100% identical), rabbit ATG4C (96% identical), pig ATG4C (94% identical), mouse Atg4c (90% identical), rat Atg4c (90% identical), macaque ATG4C (89% identical), guinea pig ATG4C (85% identical), tropical clawed frog atg4c (70% identical), zebrafish atg4c (58% identical), Drosophila melanogaster Atg4b (40% identical). Paralogues in human: ATG4D (46% identical), ATG4B (26% identical), ATG4A (25% identical).
Diseases named in the same sentence as ATG4C in open-access papers:
ATG4C is named in the same sentence as 25 diseases in open-access papers, as found by Europe PMC text mining. Sharing a sentence is not in itself a finding about the gene and the disease. The quoted sentences say what the papers report.
glioma (10 papers, 2019 to 2025). A benign or malignant brain and spinal cord tumor that arises from glial cells (astrocytes, oligodendrocytes, ependymal cells). "Taken together, our results suggested that increased ATG4C expression was associated with worse prognosis in glioma patients." (PMID 31291988, 2019). "The association between ATG4C mRNA expression and prognosis of gliomas patients was analyzed using the TCGA datasets." (PMID 31291988, 2019). "In this study, we identified that the mRNA level of ATG4C was associated with worse prognosis in glioma patients." (PMID 31291988, 2019). "Autophagy Related 4D Cysteine Peptidase (ATG4D) and its paralog gene ATG4C played an important role as autophagy regulators that linked mitochondrial dysfunction with apoptosis in cancers such as breast carcinoma, human uterine fibroids, colorectal cancer and glioma." (PMID 34238288, 2021). "Depletion of ATG4C also attenuated temozolomide‐induced autophagy and increased the chemosensitivity of glioma cells." (PMID 40883962, 2025). "Studies have shown that Atg4C knockdown suppresses glioma progression by inducing cell cycle arrest and promoting apoptosis of glioma cells, possibly by increasing reactive oxygen stress (ROS) production." (PMID 37993477, 2023). "The deletion or lower expression of important genes (Beclin-1, FIP200, blood-inducing factor 1 (Bif1), UVRAG, Atg4c and Atg5) is reported in gliomas for autophagosome initiation and elongation." (PMID 33525678, 2021). "Recently, researchers have found that ATG4C is highly expressed in glioblastomas, and its expression increased with the number of gliomas." (PMID 34636718, 2021). "When ATG4C is knocked out, the proliferation of U87MG glioma cells is inhibited by causing cell cycle arrest in the G1 process." (PMID 34204169, 2021). "Reduced ATG4C expression induced the sensitivity of the T98G and U87-MG glioma cells to TMZ by autophagy inhibition." (PMID 33525678, 2021). "Knockdown of autophagy-related 4C cysteine peptidase (ATG4C) repressed glioma progression by arresting tumor cells at the G1 phase and promoting apoptosis." (PMID 34671362, 2021). "Knockdown of ATG4C expression in gliomas can induce cell cycle arrest, thereby inhibiting cancer cell proliferation." (PMID 34636718, 2021). "A drop in the expression of ATG4C improved the sensitivity of U87-MG and T98G glioma cells to TMZ by inhibiting autophagy." (PMID 32707662, 2020). "Based on TCGA data mining, we observed that expression level of autophagy related 4C cysteine peptidase (ATG4C), a member of ATG4 family, is deeply associated with prognosis of glioma patients." (PMID 31291988, 2019). "Ectopic xenograft nude mice model was established to investigate the effects of ATG4C on glioma growth in vivo." (PMID 31291988, 2019). "Knockdown of ATG4C suppressed glioma progression by inducing cell cycle arrest and promoting apoptosis of glioma cells possibly through increasing ROS production." (PMID 31291988, 2019). "Compared with control group, knockdown of ATG4C by si-RNA transfection significantly suppressed the proliferation of glioma cells indicated by proliferation curves." (PMID 31291988, 2019). "In order to investigate the effects of ATG4C on glioma growth in vivo, a xenograft nude mouse model was established." (PMID 31291988, 2019). "The MTS assay and colony formation were performed to evaluate the role of ATG4C on glioma proliferation." (PMID 31291988, 2019).
glioma (continued). "We demonstrated that knockdown ATG4C remarkably suppressed the proliferation of glioma cell lines by inducing cell cycle arrest at G1 phase." (PMID 31291988, 2019). "In this study, we observed that ATG4C was differently expressed between normal brain and glioblastoma tissues, and its expression was increased with the grade of glioma." (PMID 31291988, 2019). "Knockdown of ATG4C markedly suppressed the growth of glioma and promoted apoptosis in glioma cells, which was accompanied by increased ROS production." (PMID 31291988, 2019). "When the patients were divided into two groups according to ATG4C mRNA expression levels, we observed that patients with higher ATG4C mRNA expression were more likely to develop advanced grades glioma." (PMID 31291988, 2019). "Consistent with the in vivo findings, knockdown ATG4C restrained the proliferation of glioma with significantly decreased tumor volumes and weights." (PMID 31291988, 2019). "This study was designed to investigate the role of ATG4C in glioma progression and temozolomide (TMZ) chemosensitivity." (PMID 31291988, 2019). "Inhibition of autophagy-related 4C cysteine peptidase (ATG4C) can arrest tumor cells in the G1 phase and promote apoptosis to inhibit the progression of glioma, indicating that autophagy may promote glioma by promoting the proliferation of tumor cell invasion." (PMID 37398678, 2023). "Furthermore, BALB/C male nude mice with ATG4C knockdown have a significant reduction in glioma development." (PMID 34204169, 2021). "And ATG4C depletion impairs TMZ-resistance and improves the susceptibility of glioma to TMZ." (PMID 34671362, 2021). "Knockdown ATG4C suppressed glioma cells proliferation by inducing cell cycle arrest at G1 phase." (PMID 31291988, 2019). "ATG4C is a potential prognostic predictor for glioma patient." (PMID 31291988, 2019). "ATG4C mRNA expression was significantly increased with the increase in glioma grade." (PMID 31291988, 2019). "Additionally, cytotoxicity of TMZ was increased while the TMZ-induced autophagy was reduced in ATG4C depleted glioma cells." (PMID 31291988, 2019). "To make clear whether ATG4C acts through affecting cell growth in gliomas, we observed its role in proliferation of gliomas cells." (PMID 31291988, 2019). "Moreover, we observed that ATG4C ablation blocked the accumulation of LC3II in the presence of BafA1 in the glioma cells treated with TMZ." (PMID 31291988, 2019). "ATG4C levels was evidently elevated with the rising of glioma grade." (PMID 31291988, 2019). "The impaired proliferation of glioma cell by si-ATG4C might be a result, at least in part, from unorganized cell cycle." (PMID 31291988, 2019). "For this reason, we analyzed the cell cycle distribution of glioma cells after ATG4C silencing." (PMID 31291988, 2019). "We then compared the expression of ATG4C mRNA in different grades of gliomas using TCGA database." (PMID 31291988, 2019). "Given that ATG4C expression was increased in tumor tissues of glioma, a therapy targeting ATG4C may provide a promising strategy for gliomas treatment." (PMID 31291988, 2019). "Moreover, ectopic xenograft nude mice model was used to establish the influence of ATG4C on glioma growth in vivo." (PMID 31291988, 2019). "However, we observed concomitantly increased protein expression of LC3-II and P62 in glioma cells transfected with si-ATG4C." (PMID 31291988, 2019). "ATG4C mRNA expression was evidently increased with the rising of glioma grade (p = 2.97 × 10− 8)." (PMID 31291988, 2019). "Moreover, ATG4C knock-out (KO) appreciably reduced the growth rate of glioma in nude mice." (PMID 33525678, 2021). "Furthermore, ATG4C KO significantly reduced glioma growth rates in nude mice." (PMID 32707662, 2020). "Development of ATG4C specific inhibitors may bring new promising strategy for glioma treatment." (PMID 31291988, 2019). "Additionally, ATG4C ablation could promote TMZ cytotoxicity to glioma cells by inhibiting autophagy." (PMID 31291988, 2019).
glioma (continued). "Additionally, ATG4C knockdown suppressed the growth of glioma remarkably in nude mice." (PMID 31291988, 2019). "However, the role of ATG4C in autophagy in glioma cells was unclear." (PMID 31291988, 2019). "Targeting ATG4C may provide promising therapy strategies for gliomas treatment." (PMID 31291988, 2019). "Depletion of ATG4C suppressed TMZ-activated autophagy and promoted sensitivity of glioma cells to TMZ." (PMID 31291988, 2019). "However, the role of ATG4C in gliomas progression and TMZ chemosensitivity remains unclear." (PMID 31291988, 2019). "Therefore, ATG4C might be potential target for the treatment of gliomas." (PMID 31291988, 2019). "In this study, we tried to determine whether interference with ATG4C can affect autophagy activity and TMZ sensitivity in glioma cell lines, as well as its role in disease progression of glioma both in vitro and in vivo." (PMID 31291988, 2019). "Although the roles of ATG4C and ATG4D in autophagy are less well‐characterized compared to ATG4A and ATG4B, knockdown of ATG4C has been shown to induce cell cycle arrest at the G1 phase and ROS‐mediated apoptosis in glioma cells, likely through suppression of autophagy." (PMID 40883962, 2025). "The role of ATG4C in autophagy in glioma cells is not clear." (PMID 31291988, 2019).
breast carcinoma (8 papers, 2017 to 2026). "ATG4A and ATG4C are required for the survival of breast cancer stem cells or mammospheres formation, showing their important roles in the progress of breast cancer." (PMID 36980240, 2023). "Previous study has shown that ATG4C is involved in the maintenance of stem-like phenotype in breast cancer cells." (PMID 31291988, 2019). "Highlighting ATM expression showed a significant positive correlation with the expression of autophagic gene ATG4C among microarray data derived from 511 breast cancer samples." (PMID 28423511, 2017). "Our results give novel insights into the molecular mechanisms underlying mammosphere formation attributing a previously unrecognised role in this process to the crosstalk between ATM kinase and ATG4C autophagic gene in breast cancer progression." (PMID 28423511, 2017). "Remarkably, we were able to show a correlation between ATM and ATG4C expression in all breast cancer subtypes except for the basal-like one underscoring a clinical impact of our findings." (PMID 28423511, 2017). "They concluded that ATM and ATG4C in breast cancer cells are essential drivers of mammosphere formation, suggesting that targeting them may improve current approaches to eradicate breast cancer cells with a stem-like phenotype." (PMID 36612206, 2022). "Likewise, they observed a significant correlation between ATM and ATG4C expression levels in all human breast cancer subtypes except the basal type." (PMID 36612206, 2022). "Additionally, in breast cancer and hepatocellular carcinoma, silencing the ATG4C gene can inhibit the occurrence of autophagy, thus affecting tumor development." (PMID 34636718, 2021). "Previous researches suggested that the miR-376 mediated ATG4C silencing could suppress autophagy in breast cancer cells and hepatocarcinoma cells." (PMID 31291988, 2019). "To further evaluate the clinical significance of our findings, we asked whether we could identify a significant correlation between ATM and ATG4C expression in breast cancer human samples." (PMID 28423511, 2017). "Finally, tumor array analyses, performed using public data, identify a significant correlation between ATM and ATG4C expression levels in all human breast cancer subtypes, except for the basal-like one." (PMID 28423511, 2017). "We demonstrate that, in breast cancer cells, ATM and ATG4C are essential drivers of mammosphere formation, suggesting that their targeting may improve current approaches to eradicate breast cancer cells with a stem-like phenotype." (PMID 28423511, 2017).
diabetes (2 papers, 2018 to 2022).
epithelial ovarian cancer (2 papers, 2020 to 2025). "Association between CAV1 and ATG4C protein expression in epithelial ovarian cancer tissues." (PMID 32401768, 2020). "Clinicopathologic features and distribution of CAV1 and ATG4C in the stroma of 79 epithelial ovarian cancer patients." (PMID 32401768, 2020). "Clinicopathologic features and distribution of CAV1 and ATG4C in cancer cells of 95 epithelial ovarian cancer patients." (PMID 32401768, 2020). "However, the clinical significance of CAV1 and ATG4C expression in epithelial ovarian cancer (EOC) remains largely unknown." (PMID 32401768, 2020).
glioblastoma (2 papers, 2019 to 2021). The most malignant astrocytic tumor (WHO grade IV). "As compared with normal brain tissues, the expression of ATG4C mRNA was significantly higher in glioblastoma tissues." (PMID 31291988, 2019). "b ATG4C knockdown suppressed the proliferation of primarily cultured glioblastoma cells." (PMID 31291988, 2019). "Additionally, we observed that knockdown ATG4C could restrain the proliferation of primarily cultured glioblastoma cells from patients." (PMID 31291988, 2019).
adenoma (1 paper, 2012). A neoplasm arising from the epithelium. "Subsequent studies demonstrated that Atg5-/- and Atg7-/- livers give rise to adenomas, Atg4C-/- mice are susceptible to chemical carcinogenesis, and Bif1-/- mice are prone to spontaneous tumors, indicating that autophagy defects promote tumorigenesis." (PMID 23181220, 2012).
cervical cancer (1 paper, 2021). A primary or metastatic malignant neoplasm involving the cervix. "ATG4C expression is decreased in cervical cancer, but it is a risk factor in the prognosis model, it is worthy of further study." (PMID 34238288, 2021). "Finally, among the 12 autophagy biomarkers related to the survival of cervical cancer, based on literature search, we selected 6 genes (ATG4C, ATG4D, CD46, TP73, SERPINA1 and HSPB8) to verify their RNA expression in CC and normal cervical tissue samples." (PMID 34238288, 2021).
fibrosarcoma (1 paper, 2019). A malignant mesenchymal fibroblastic neoplasm affecting the soft tissue and bone. "Knockout of ATG4C increased the susceptibility to develop fibrosarcomas induced by methylcholanthrene in mice, suggesting that ATG4C may play a tumor-suppressor role." (PMID 31083460, 2019).
liver cancer (1 paper, 2017). An epithelial or non-epithelial malignant neoplasm that arises from the liver. "In addition to BECN1/Beclin 1, miR-376 family members miR-376a and miR-376b could negatively regulate ATG4C in breast and liver cancer cells." (PMID 28459042, 2017). "miR-376a and miR-376b regulated starvation- and rapamycin-induced autophagy in breast and liver cancer cells by directly targeting 3′-UTR sequences of BECN1/Beclin 1 and ATG4C." (PMID 28459042, 2017).
neuropathy (1 paper, 2024). A disorder affecting the nervous system that manifests with pain, tingling, numbness, and/or muscle weakness. "Specific genes increased in patients withoutlinezolid-associated neuropathy included ATG4C, BAX, and IGF1, while patients onlinezolid who suffered from neuropathy had an increase in AURKB, CASP3, CASP8, CDK1,CDKN1B, CEBPB, NADSYN1, NRF1, GPX7, and SBSN." (PMID 38939039, 2024).
Obesity (1 paper, 2022). Accumulation of substantial excess body fat.
osteosarcoma (1 paper, 2025). A usually aggressive malignant bone-forming mesenchymal neoplasm, predominantly affecting adolescents and young adults. "This study suggested that silencing ATG4 family members (ATG4A, ATG4B, ATG4C, and ATG4D) led to an increased proportion of cells in the G1 phase in osteosarcoma cells." (PMID 40883962, 2025).
psoriasis (1 paper, 2025). An autoimmune condition characterized by red, well-delineated plaques with silvery scales that are usually on the extensor surfaces and scalp. "We found the expression of the gene ATG16L to be significantly suppressed and that of the genes ATG3 and ATG4C to be significantly higher in the lesional skin of psoriasis patients compared to controls and to non-lesional skin." (PMID 40565008, 2025).